WRN (WRN RecQ like helicase)
Diseases named in the same sentence as WRN in open-access papers (continued):
Sharing a sentence is not in itself a finding about the gene and the disease.
Werner syndrome (continued). "Because Werner syndrome is caused by mutations in WRN gene that encodes a RecQ DNA helicase important to DNA replication and chromatin maintenance, genomic instability and heterochromatin disorganization manifest in WS pathogenesis." (PMID 30069858, 2019). "None of the heterozygous or homozygous carriers of this mutation developed Werner Syndrome (as defined by the clinical phenotype), clearly separating the WRN helicase function from other WRN functions." (PMID 31276497, 2019). "The Werner's syndrome protein (WRN) is one of these key factors, and is mutated in the genetic disease Werner's syndrome (WS), which is characterized by cancer predisposition and premature aging." (PMID 31114910, 2019). "Mutations in PRKAR1α cause Carney complex, while disturbances of the WRN gene signaling pathway are associated with development of Werner syndrome." (PMID 31247975, 2019). "Whole genome sequencing was done and the patient was found to be homozygous for WRN mutation, confirming the diagnosis of Werner syndrome." (PMID 31363425, 2019). "Mutations in the WRN gene cause the Werner syndrome (WS), a human disorder associated with chromosomal instability and cancer predisposition." (PMID 30657978, 2019). "More than 80 different homozygous or compound heterozygous mutations in the Werner syndrome (WRN) gene have been associated with WS." (PMID 31259468, 2019). "The changes in H3K9me3 in Werner syndrome are likely due to WRN-guided heterochromatin because WRN associates with KMT1/SUV39H and HP1." (PMID 30373515, 2018). "Both the ocular symptoms and systemic signs combination with the homozygous WRN mutation indicated the definitive Werner’s syndrome diagnosis." (PMID 30107835, 2018). "To explore the relationship between protein quality control and human stem cell aging, we checked the expression of a series of UPR proteins in replicative senescent hMSCs and premature aging (Werner Syndrome, WRN-deficient) hMSCs27–30." (PMID 29423270, 2018). "Werner syndrome is caused by recessive mutations in the RECQL2 protein encoding WRN gene that result in a loss of protein by creating new stop codons or cause frameshifts resulting in a premature stop codon." (PMID 30140252, 2018). "We specifically examined changes in the expression of Werner syndrome helicase (WRN) because mutations in WRN protein cause an advanced aging disorder known as adult progeria." (PMID 30373515, 2018). "Bi-allelic mutations in the WRN gene result in Werner syndrome (WS), a progeroid disease considered by many to most closely resemble accelerated aging." (PMID 29998112, 2018). "We observed that the expression levels of Nrf2 and GPx7 decreased in both replicative senescent HMSCs and premature senescent HMSCs (Werner syndrome‐specific: WRN‐deficient)." (PMID 29659168, 2018). "The ocular and systemic findings in this patient in combination with the homozygous WRN mutation indicated the definitive Werner’s syndrome diagnosis." (PMID 30107835, 2018). "The definitive diagnosis for Werner’s syndrome is based on the genetic analysis for mutations in the WRN gene." (PMID 30107835, 2018). "WRN is an ATP-dependent helicase with exonuclease activity that, when mutated, leads to the development of Werner syndrome." (PMID 30189661, 2018). "Mutations in WRN cause the Werner syndrome, which is associated with premature ageing and an increased cancer susceptibility." (PMID 29084988, 2017). "Loss-of-function mutations in the WRN helicase gene cause Werner syndrome- a progeroid syndrome with an elevated risk of cancer and other age-associated diseases." (PMID 28276523, 2017). "From a structural and mechanistic standpoint, the best studied of the helicase-RPA interactions is that of the Werner syndrome (WS) helicase-nuclease (WRN) that is implicated in one of the most striking accelerated aging disorders." (PMID 28594346, 2017).
Werner syndrome (continued). "WRN mutations of the gene lead to Werner syndrome, which is characterized by genetic instability and hematological disease." (PMID 27829440, 2016). "Mutations in three of them [WRN (Werner syndrome, RecQ helicase-like), BLM (Bloom syndrome, RecQ helicase-like) and RECQ4 (RecQ helicase-like 4)] are associated with WS, BS and RTS premature-ageing syndromes, respectively." (PMID 27482812, 2016). "Werner syndrome is a progeroid disease characterised by genetic instability due to mutations to the WRN helicase/exonuclease." (PMID 27063109, 2016). "PARP1 has also been linked to aging, being present in a complex with WRN DNA repair proteins that are deficient in participants with Werner syndrome, a premature aging syndrome." (PMID 27824314, 2016). "The WRN gene, mutated in the premature aging disorder Werner syndrome, encodes a protein with both DNA helicase and exonuclease activities." (PMID 25906194, 2015). "Telomeric abnormalities caused by loss of function of the RecQ helicase WRN are linked to the multiple premature ageing phenotypes that characterize Werner syndrome." (PMID 26420422, 2015). "Deficiencies in WRN cause Werner syndrome, which is a rare autosomal recessive disorder characterized by premature aging and cancer susceptibility." (PMID 26241669, 2015). "The loss of WRN helicase leads to abnormalities at chromosome ends and is associated with premature ageing phenotypes characteristic of Werner syndrome." (PMID 26420422, 2015). "For example, only recently were several WRN missense mutations genetically linked to the premature aging disorder Werner syndrome identified and found to be in conserved catalytic domains of the WRN protein." (PMID 25374583, 2014). "Werner syndrome is caused by mutations in the gene that encodes a protein named Werner syndrome protein (WRN) with helicase and exonuclease activity." (PMID 24757718, 2014). "We show here that lipodystrophy and extreme insulin resistance can also reveal the adult progeria Werner syndrome linked to mutations in WRN, encoding a RecQ DNA helicase." (PMID 23849162, 2013). "Hereditary germ line mutations in the WRN gene cause the adult-progerioid genetic disorder known as Werner’s syndrome (WS)." (PMID 24308539, 2013). "The best known example of an adult-onset segmental progeroid syndrome is the Werner syndrome (“Progeria of Adult”; WS), caused by mutations in the WRN gene." (PMID 23847654, 2013). "Among this set of candidate annotations, the gene WRN (“Werner syndrome, RecQ helicase-like”) was linked to the disease Werner syndrome and the gene CRYGC (“crystallin, gamma C”) was linked to cataracts." (PMID 23951102, 2013). "Here we report the cases of two women investigated for lipodystrophy and severe insulin resistance, which revealed Werner syndrome due to homozygous or compound heterozygous, non-sense or frameshift mutations in the WRN gene." (PMID 23849162, 2013). "Werner syndrome, a rare but highly informative premature ageing syndrome, is caused by mutation of the human WRN gene which encodes a large protein (hWRN) possessing both helicase and exonuclease activities." (PMID 22562358, 2013). "Werner syndrome (WS) is an autosomal recessive genetic disease that is caused by mutation of the WRN gene." (PMID 22797812, 2012). "Mutations in the WRN gene cause Werner syndrome, associated with premature aging, genome instability and cancer predisposition." (PMID 22713343, 2012). "WRN has roles in DNA replication and repair, transcription, and telomere maintenance, and defects in WRN cause Werner syndrome, an autosomal recessive disorder associated with premature aging." (PMID 21346809, 2011). "Werner syndrome, arising from mutations in the WRN helicase gene, causes premature aging in young adults." (PMID 21931180, 2011). "Loss of WRN gives rise to the Werner syndrome, a genetic disease characterised by premature aging and cancer predisposition." (PMID 21389352, 2011).
Werner syndrome (continued). "WRN is a cancer gene in which germline mutation causes Werner syndrome, a condition associated with markedly increased risk of bone tumors, and in which somatic inactivating mutations have been documented in renal cancer." (PMID 21215367, 2011). "Arguably the most well-known example of such progeroid syndromes is Werner's syndrome, caused by a mutation in the WRN gene, which encodes a DNA helicase and exonuclease protein." (PMID 21226956, 2011). "The protein linked to Werner syndrome, WRN, has both helicase and exonuclease activities and is thought to be involved in DNA repair, including the resolution of replication fork arrest as well as in telomere maintenance." (PMID 20062519, 2010). "In the last ten years the discovery of the mutant gene that encodes for the WRN protein has permitted us to define the molecular pathology of Werner syndrome, a rare autosomal recessive genetic disorder exhibiting premature ageing." (PMID 27713332, 2010). "Werner syndrome is an autosomal recessive disease of premature aging caused by a polymorphic C1367T mutation in the Werner (WRN) gene." (PMID 20808731, 2010). "Werner syndrome is a prematureaging disease caused by loss of function mutations in the Werner syndromeprotein (WRN) gene." (PMID 20157518, 2009). "Werner syndrome (WS) is apremature aging disorder characterized by genomic instability.The WRN gene defective in WS encodes a protein with both helicaseand exonuclease activities that interacts with proteins implicated in DNAmetabolism." (PMID 20157511, 2009). "Werner syndrome (WS) is an autosomal recessive segmental progeria caused by mutations in the gene encoding Werner protein (WRN)." (PMID 18398454, 2008). "For example, the human WRN helicase defect causes the premature aging Werner syndrome, while mutation of Sgs1 helicase, the WRN homolog in yeast, causes the shortening of replicative lifespan." (PMID 18691183, 2008). "Recessive mutations in WRN gene eliminate WRN protein function (helicase) and cause Werner syndrome." (PMID 18312663, 2008). "The cancer-prone and accelerated aging disease Werner syndrome is caused by loss of function of the WRN gene product that possesses ATPase, 3' to 5' helicase and 3' to 5' exonuclease activities." (PMID 16503984, 2006). "The cause of premature aging in Werner syndrome patients may be due to the ability of WRN to regulate the transcription of NMNAT1, a key enzyme in NAD+ biosynthesis." (PMID 39759116, 2025). "Werner syndrome (WS) is a rare hereditary progeroid syndrome caused by mutations in the WRN gene." (PMID 40459998, 2025). "Mutations in the Werner syndrome (WRN) gene cause premature aging during early adulthood, but the role of this exonuclease in natural aging remains unclear." (PMID 40261911, 2025). "Likewise, lamin A (LMNA) deficiency and the depletion of the DNA repair gene WRN, which occurs in Werner Syndrome (WS) and causes premature aging, leads to H3, SETDB1, SUV39H1 and HP1 deregulation, contributing to heterochromatin loss and DNA damage." (PMID 40886198, 2025). "Subsequently, we conducted the CRISPR screening in three types of stem cell senescence models, including replicative senescent hMSCs (RS hMSCs), Werner syndrome (WS, WRN-deficient) hMSCs, and Hutchinson-Gilford progeria syndrome (HGPS, carrying the heterozygous LMNAG608G/+ mutation) hMSCs." (PMID 38894586, 2025). "A direct link between compromised stalled fork recovery and aging has been established by characterizing the molecular phenotypes of cells isolated from individuals with Werner Syndrome (WS), an autosomal recessive premature aging disease resulting from loss-of-function mutations in the WRN gene." (PMID 38777831, 2024). "Moreover, WRN is critical for Werner syndrome and is associated with various mutations in cancer types such as peritoneal, colon, and stomach cancer." (PMID 39455841, 2024). "Interestingly, Werner syndrome with mutations in the WRN gene has also been identified in the third cluster." (PMID 36435816, 2022).
Werner syndrome (continued). "Werner syndrome (WS) is an autosomal recessive progeroid syndrome caused by variants in WRN." (PMID 35534204, 2022). "Interestingly, several variants were observed in genes that have not been well characterized in patients with prostate cancer, including the tumor suppressor gene FANCA as well as WRN, which is associated with the premature aging disease Werner's syndrome." (PMID 36446039, 2022). "Pathogenic mutations in WRN are a cause of premature aging disease Werner syndrome (WS)." (PMID 36587229, 2022). "In this respect, any abnormality or mutation in DNA repair pathways—such as Werner’s syndrome caused by a mutation in Werner’s syndrome protein (WRN), a gene that encodes a RecQ DNA helicase essential for replication stress management and telomere stability —causes rapid aging and shorter lifespan." (PMID 35408714, 2022). "Werner syndrome is an autosomal recessive condition caused by biallelic pathogenic variants in WRN." (PMID 35359366, 2022). "The nuclear localization signal is located in the C-terminal region of WRN, and mutations in these sequence result in the translocation of WRN to the nucleolus and account for a significant portion of the mutations that drive the pathogenesis of Werner syndrome (WS)." (PMID 33718381, 2021). "Werner’s Syndrome (WS) is one of several rare premature aging syndromes with links to cancer, and its etiology stems from the loss of helicase and exonuclease activities of the WRN protein." (PMID 34621683, 2021). "Similar to RTS patients, mutations in another RecQ helicase, WRN, results in Werner syndrome." (PMID 34946868, 2021). "WRN mutation causes a premature aging disease called Werner syndrome (WS)." (PMID 32320127, 2020). "Werner syndrome features inactivating biallelic mutations of WRN, a DNA helicase." (PMID 31293201, 2019). "Mutations in WRN lead to Werner syndrome with systemic aging phenotypes." (PMID 31921313, 2019). "Interestingly, telomere sequences and G4 structures are also substrates of the WRN helicase, null mutations at which are responsible for a segmental progeroid syndrome, the Werner syndrome (Croteau, Popuri, Opresko, & Bohr, 2014)." (PMID 30393977, 2018). "Werner syndrome is the most common accelerated-aging syndrome derived from DNA repair defects, caused by the mutations of Werner syndrome ATP-dependent helicase (WRN), a gene coding for a protein implicated in telomere maintenance and homology-dependent recombination repair." (PMID 30405405, 2018). "Mutations in WRN can cause Werner syndrome, a rare disease associated with premature aging." (PMID 29270911, 2018). "A chemical screen was later performed on these WRN-deficient MSCs, and interestingly, Vitamin C was found to be able to rescue many of the aging features, suggesting it be a potential treatment to alleviate Werner syndrome." (PMID 28102490, 2017). "Werner syndrome is caused by mutations in the WRN gene encoding WRN helicase." (PMID 28266653, 2017). "Loss of WRN gives rise to a genetic disease known as Werner syndrome (WS)." (PMID 26860083, 2016). "We also tested another human RecQ helicase, WRN which is implicated in Werner Syndrome." (PMID 25409515, 2014). "More than 30 WRN mutations have been identified in patients with Werner syndrome." (PMID 24620826, 2014). "The WRN protein is associated with Werner's syndrome, considered the progeroid syndrome that most presents characteristics of accelerated ageing, and the WRN protein is a hub (a node with a large number of neighbours) in ageing-related protein interaction networks." (PMID 21226956, 2011). "Mutations in the WRN gene give rise to a severe human disease: the Werner syndrome (WS)." (PMID 21389352, 2011). "HGPS is termed progeria of the infancy because the clinical phenotype starts manifesting after the first years of life, while aWS clinically resembles another condition -the classical Werner syndrome- produced by mutations in the WRN gene and causes progressive degeneration during adulthood." (PMID 21483033, 2011).
Werner syndrome (continued). "We speculated that a search for the C1367T WRN polymorphism responsible for Werner syndrome in elderly patients with cataract might shed light on the molecular basis of both the disease and the normal aging process of the eye." (PMID 20808731, 2010). "Mutations in the WRN gene cause Werner syndrome (WS), a rare autosomal recessive disorder." (PMID 20428248, 2010). "Although T-oligos do not act as telomerase inhibitors or cause digestion of the 3' telomere overhang, T-oligos have been shown to rapidly concentrate in nuclei when added to cultured cells and the subsequent responses require WRN, the protein mutated in the progeroid cancer-prone Werner syndrome." (PMID 20846433, 2010). "Interestingly, PARP, and DNA-PKcs have been shown to interact/cooperate with WRN, the protein mutated in the premature aging Werner syndrome, raising the possibility of tankyrase 1 specific involvement in aging." (PMID 21037379, 2010). "Loss of WRN causes the progeroid disorder Werner syndrome which is marked by cancer predisposition." (PMID 19283071, 2009). "The WRN protein is a member of the human RecQ helicases and is found mutated in the genetic disease Werner syndrome (WS)." (PMID 38764946, 2024). "Werner syndrome (WS) is a rare monogenic premature aging disorder caused by WRN, a gene that encodes a RecQ-type DNA helicase which is involved in DNA replication and repair." (PMID 37793000, 2023). "Werner syndrome (WS) is a rare autosomal recessive disease caused by a gene mutation in the WRN gene, and it is classified as a premature aging disorder, with an estimated prevalence of 1:380,000 to 1:1,000,000." (PMID 38104125, 2023). "WS is caused by a mutation in the WRN gene, which encodes for Werner syndrome ATP-dependent helicase." (PMID 37895059, 2023). "Another member of the Rec family, WRN, is associated with Werner syndrome (WS; OMIM #277700) and increases the risk of thyroid carcinoma, melanoma, breast cancer and meningioma as well as soft tissue and bone sarcomas." (PMID 37762649, 2023). "Similarly, homozygous and compound heterozygous loss-of-function mutations in WRN is associated with Werner syndrome, which is characterized by premature aging, skin changes (scleroderma), short stature, osteoporosis, cataracts, diabetes, hypogonadism, and premature atherosclerosis." (PMID 35267530, 2022). "The Progerin-inhibitor (SLC-D011) could ameliorate senescence in the fibroblasts and cardiomyocytes derived from Werner syndrome-iPSCs, suggesting that Progerin is able to accumulate and cause aging phenotype under WRN-deficient conditions and the phenomenon may be prevented by SLC-D011." (PMID 35205210, 2022). "Defects in BLM and WRN cause autosomal disorders: Bloom syndrome (BS) and Werner syndrome (WS), respectively." (PMID 33718381, 2021). "Werner syndrome (WS) is an adult-onset progeroid disease in which mutations in the gene encoding the Werner syndrome protein (WRN) are thought to cause abnormal cell function." (PMID 33646120, 2021). "Mutations in WRN, a gene that encodes a helicase responsible for managing replication stress and telomere stability, cause Werner syndrome (WS)." (PMID 33512317, 2021). "The mutation or loss of three genes BLM, WRN or RecQ4 leads to related diseases, which are Bloom syndrome (BS), Werner syndrome (WS) or Rothmund-Thomson syndrome (RTS), respectively." (PMID 34606619, 2021). "Werner syndrome (WS) is an accelerated aging disorder characterized by genomic instability, which is caused by WRN protein deficiency." (PMID 34612580, 2021). "Patients with Werner Syndrome (WS) harbor a mutation in the WRN gene that leads to loss of telomere maintenance, premature aging and increased cancer rates." (PMID 34017357, 2021). "For example, WRN protein, mutated in Werner syndrome (WS) characterized by premature aging in young adults, is involved in both homologous recombination (HR) and non-homologous end joining (NHEJ) pathways." (PMID 33143308, 2020).